PARP1 (poly(ADP-ribose) polymerase 1)
Diseases named in the same sentence as PARP1 in open-access papers (continued):
Sharing a sentence is not in itself a finding about the gene and the disease.
cancer (continued). "PARP1, a well-known cancer-promoting factor, is highly expressed in multiple tumors, which induces poor prognosis of patients." (PMID 33741027, 2021). "Defects in a given repair pathway or inappropriate repair pathway choice can be exploited for synthetic lethal cancer therapy approaches, such as poly(ADP-ribose) polymerase 1 (PARP1) inhibition, which selectively kills HR-deficient cancers." (PMID 34745220, 2021). "Media transfer experiments and the use of the PARP1 inhibitor, Olaparib, confirmed PARP1 involvement in RIRE in various carcinoma cell lines (HeLa, MCF7, CNE-2 and HCT116)." (PMID 34680868, 2021). "Although many DNA repair enzymes, such as PARP1, are considered as therapeutic targets, the advantage of selectively targeting DNA glycosylases in cancer and neurodegenerative diseases has emerged only recently." (PMID 32192183, 2020). "Nonetheless, these data strongly suggest that XRN2 vulnerabilities in cancers can be exploited by pharmacological inhibition of PARP1." (PMID 32859985, 2020). "Several studies have investigated the role of c‐MET or PARP‐1 inhibition as putative targets for cancer therapy." (PMID 32686903, 2020). "To determine the effect of PARP deletion in the entire cancer environment on bone metastasis, we examined PARP1 or PARP2 global knockout (KO) mice." (PMID 32221289, 2020). "This presence of these abnormalities in cancer cells led to the development of PARP-1 inhibitors as a new class of anti-cancer therapy." (PMID 32373151, 2020). "Due to its pivotal role in DNA damage response, inhibition of PARP-1 is emerging as a useful therapeutic approach for cancers." (PMID 32779949, 2020). "For example, the known synthetic lethal interactions between the tumor suppressor gene BRCA1/2 and the drug target gene PARP1 can be used to selectively kill cancer cells by triggering fatal DNA damages." (PMID 32184722, 2020). "On the other hand, PARP1 is the primary target for a novel cancer therapeutic modality based on the synthetic lethality paradigm." (PMID 32392755, 2020). "Targeting the PARP1-mediated DNA repair pathway has recently received considerable attention as an approach for enhancing the effects of anti-cancer drugs and radiation therapy." (PMID 32405340, 2020). "Taken together, PARP1 overexpression in various cancers can be exploited as a molecular target in the clinic." (PMID 32640708, 2020). "Based on PARP1’s role in DNA repair, early prognoses for the role of its inhibitors in cancer therapy were to enhance antitumor activity of radio- or chemotherapy." (PMID 32106627, 2020). "We demonstrate that CAPE-MotAb cause a stronger dose-dependent growth arrest/apoptosis of cancer cells through the downregulation of Cyclin D1-CDK4, phospho-Rb, PARP-1, and anti-apoptotic protein Bcl2." (PMID 32825706, 2020). "It has been found that inhibition of PARP1 and deficiency of BRCA1/2 synergistically kill BRCA1/2-deficient breast and other cancer cells via inhibiting DNA repair." (PMID 33665167, 2020). "The cancer tissues showed decreased DNA methylation in the promoter region of PARP1 compared to that in healthy tissues." (PMID 32594311, 2020). "Accordingly, in cancer cells, post-transcriptional regulations of Parp-1 has been described by cellular miRNAs78,79." (PMID 32641757, 2020). "The trapped PARP1 triggers further DNA damage, cell cycle arrest, and eventually, cancer cell death." (PMID 32844745, 2020). "The activity of PJ34 in cancer cells has been suggested to promote cell death by preventing PARP1-mediated DNA repair." (PMID 32575437, 2020). "Inhibition of PARP1 leads to accumulation of single and double strand DNA breaks resulting in genomic instability and apoptosis in cancer cells." (PMID 32380701, 2020).
cancer (continued). "High expression of PARP1 usually increases MMEJ and genomic instability, along with highly inaccurate repair leading to mutation or cancer." (PMID 33324554, 2020). "In suppressing the invasion of cancer cells, siRNA-mediated PARP1 inhibition leads to a reduction in epithelial-to-mesenchymal transition (EMT) via upregulation of E-cadherin and downregulation of vimentin." (PMID 32784981, 2020). "PARP1 is one of the best characterized enzymes in DNA repair and an attractive target for drug design in cancer therapies." (PMID 33050515, 2020). "It has long been known that inhibition of PARP1/2 sensitizes cancer cells to ionizing radiation and DNA-damaging genotoxic agents independent of HR status." (PMID 32029902, 2020). "For example, c-Met, a receptor tyrosine kinase that is overexpressed in various cancers, phosphorylates PARP1 at Tyr907." (PMID 32405340, 2020). "Several proteins involved in the DNA damage response have been identified as emerging targets for cancer treatment, including; PARP1, ATR, and Chk1." (PMID 32850380, 2020). "As poly adenosine diphosphate (ADP)-ribose polymerase 1 (PARP-1) is overexpressed in various cancer types, and is localized to the nucleus, PARP-1 can be safely targeted with Auger emitters to induce DNA damage in tumors." (PMID 33352773, 2020). "This study adds OGG1 to the list of BER factors, e.g. PARP1, as potential targets for cancer treatment." (PMID 33211885, 2020). "In several preclinical models, combinations of NAMPT and PARP-1 inhibitors have been shown to induce cancer cell death and tumor regression, revealing a synthetic lethal interaction between NAMPT and PARP-1 deficiencies." (PMID 32807821, 2020). "Here, we provide an overview of our current understanding on the role of PARP1 in nucleolar functions and discuss potential implications in cancer biology and therapy." (PMID 32640701, 2020). "Here, therapeutic radionuclides, i.e., α, β-, and auger emitters, were conjugated to PARPis with the goal of effectively inflicting DNA damage on cancer cells, as binding to PARP1 leads to radioactive decay events in close proximity of the DNA." (PMID 32640708, 2020). "PARP1, due to its amplification in a large variety of cancers and essential role in DNA damage repair, has emerged as a potent anticancer target." (PMID 32380701, 2020). "The PARP1 tracers discussed in this work have been evaluated in various cancer types, which all show PARP overexpression." (PMID 32640708, 2020). "The recent development of PARP1 inhibitors for the treatment of cancers presenting compromised HR repair has led to interesting findings on biomarkers associated with their clinical use against MM." (PMID 32867073, 2020). "Mechanistically, the high level of ROS in cancer promotes the activation and translocation of cMET into the nucleus where it directly binds and phosphorylates the tyrosine residue 907 (Y907) of PARP1 to enhance its enzymatic activity." (PMID 32295316, 2020). "Presently, the majority of PARP‐1 inhibiting cancer therapies are competitive antagonists of NAD+, which is the substrate for PARP‐1." (PMID 32342655, 2020). "PARP1 plays a significant role in preserving genome stability and performing DNA repair, ensuring the growth and proliferation of cancer cells." (PMID 32784981, 2020). "In the present study, we investigated PARP-1 as a unique molecular target that is highly expressed in cancer nuclei for the delivery of theranostic Auger emitting radionuclides." (PMID 33352773, 2020). "Perturbation of the PARP-1/PARG balance by the over-expression of PARG has been also shown to alter the genome methylation pattern to that of cancer cell types." (PMID 32344695, 2020).
cancer (continued). "The overexpression of PARP1 has been found in different cancers including GBM; indeed, it has been demonstrated that PARP inhibitors, alone or in combination with chemotherapeutic agents, induced promising effects against tumors harboring DNA repair defects." (PMID 33375627, 2020). "Cytoplasmic HMGB1 is a BECN-1 binding protein, which forms autophagosomes via poly-ADP-ribosylation by PARP-1 in cancer cells, which in turn contribute to reduced drug sensitivity through autophagy upregulation." (PMID 33158052, 2020). "The overexpression of PARP1 in several types of cancer further evoked interest in its use as an imaging target." (PMID 32640708, 2020). "In this work, we show that, besides inhibition of cell cycle, grapefruit-derived NVs and MVs also trigger apoptosis through the activation of PARP-1, thus further contributing to limit cancer proliferation in vitro." (PMID 33371199, 2020). "Together, PARP1 inhibitor and HRD accumulate the critical DSB damage in the BRCA-mutated cancer cells." (PMID 32269964, 2020). "This drug inhibits PARP1, a protein implicated in BER, which is often over-expressed in various types of cancers." (PMID 32252452, 2020). "Phosphorylation of PARP1 at Tyr907, mediated by c-Met, increased PARP1 enzymatic activity and reduced its binding to PARPi, thereby rendering cancer cells resistant to PARPi." (PMID 32563252, 2020). "Due to these functions, PARP-1 inhibitors have been developed as the first class of cancer therapeutics in clinical trials." (PMID 32509471, 2020). "The strategic selection of these genotyped SNPs based on functional importance alongside imputed SNPs that share an LD block has the potential to identify complex biological links among SNPs derived from PARP1 functional domains and cancer processes." (PMID 33284833, 2020). "It is worth to note that for TNBC, DNA damage of cancer cells was observed during chemotherapy and inhibiting PARP-1 is important to block DNA repair mechanisms." (PMID 32138292, 2020). "In SW620 cells, our probe-quality degrader compound 2 effectively induced PARP-1 degradation which results in anti-proliferation, cells apoptosis, cell cycle arresting, and cancer cells migratory inhibition." (PMID 32779949, 2020). "Here, we show that the aberrant activation of E2F1 found in several types of cancer can be alleviated by inactivating PARP1." (PMID 33050515, 2020). "Rescuing HDAC6 or USP10 in USP10 knockdown cancer cells yielded a high survival rate and less PARP-1 cleavage." (PMID 32382008, 2020). "PARP1 expression is increased in different cancer types, particularly at advanced stages, and in some cases correlates positively with the cytotoxic effects of PARP inhibition." (PMID 32029455, 2020). "ROS and NO damage DNA and modulate the activity of PARP-1, a protein largely involved in cancer progression that also regulates HIF-1α response." (PMID 32286485, 2020). "Although BRCA1m are highly heterogeneous and therefore difficult to target, BRCA1 gene's synthetic lethal pair, PARP1, is conserved in BRCA1m cancer cells." (PMID 31989039, 2020). "PARP1 inhibitors have been approved as a human cancer therapy and will be discussed further in this review." (PMID 32850380, 2020). "The most crucial activity of PARP1, not only in myeloid lineage malignancies but in cancer cells in general, encompasses its involvement in base excision repair (BER)." (PMID 32900001, 2020). "While APE2 had a significant (α = 0.05) positive correlation with PCNA, APE1, XRCC1, PARP1, Chk1, and Chk2 across all 6 cancer types, groupings of DNA repair and DDR genes were found to be correlated with APE2 in different patterns in different cancer types." (PMID 32111912, 2020). "Inhibitors of PARP-1 have also been developed to enhance the sensitivity of cancer cells to radiotherapy." (PMID 32355263, 2020).
cancer (continued). "In particular, knowledge of the basic biology and roles of PARP1 in DNA repair pathways led to the development of PARPi, for the targeted treatment of BRCA-mutated cancers." (PMID 33015058, 2020). "The first drugs that act by the principle of synthetic lethality, and currently still the only approved synthetically-lethal drugs for clinical use in cancer patients, are the PARP1/2 inhibitors (PARPis)." (PMID 32784607, 2020). "Thus, PARP1 inhibitors could potentially target cancers exhibiting deficiency in XRN2 function." (PMID 32859985, 2020). "Cancer cells that have deficiencies in HR, for example due to mutations in the tumor suppressor genes BRCA1 or BRCA2, are unable to repair DNA damage when PARP1 is inhibited." (PMID 33053746, 2020). "High PARP1 expression was found to lead to acquired chemotherapeutic drug resistance, and PARP1 has thus been explored for its therapeutic potential in cancer treatment." (PMID 32483468, 2020). "Twenty genes were found mutated orwith copy number alterations in at least five percent of three cancer cohortsand six of them (PHOX2A, NFYC, EST2, EIF2S1, SSRP1 and PARP1) associated withimpacted patient survival." (PMID 32159609, 2020). "Thus, PARP1 inhibition could target cancers exhibiting XRN2 functional loss." (PMID 32859985, 2020). "Calcium release from the ER can be blocked with the calcium chelator, BAPTA-AM, which prevents PARP1 hyperactivation and spares cancer cells from lethality, further highlighting the role of PARP1 in β-lap-induced cell death." (PMID 32974194, 2020). "In conclusion, we validate OGG1 as one more to the list of existing BER factors, e.g., PARP1, as potential targets for treatment of cancer." (PMID 33211885, 2020). "However, recent studies indicate that the therapeutic potential of attenuating PARP1 activity in recalcitrant tumors, especially where PARP1 is aberrantly overexpressed and hyperactivated, may extend its therapeutic utility in wider cancer types beyond BRCA-deficiency." (PMID 32295316, 2020). "The cleaved PARP1 expression was remarkably increased, indicating the DNA damage of cancer cells induced by MRT68921." (PMID 32873786, 2020). "This suggests that hyperactivation of PARP1 is essential to facilitate the repair of potentially lethal DNA breaks for the survival of HR-defective (HRD) cancers." (PMID 32295316, 2020). "The trapped PARP-1 complexes are considered to be even more deleterious for cancer cells than unrepaired DNA strand breaks, because PARP-1 protein tightly bound to DNA interferes with transcription, replication, and DNA repair." (PMID 32245127, 2020). "PARP1/2 duo-enzymatic inhibitors have been developed for cancer therapy, presumably by blocking PAR-dependent SSB repair." (PMID 32890402, 2020). "We demonstrated that the ability to induce PARP1 trapping is the primary driver for the PARPi-mediated cytotoxicity and activation of innate immune signaling in cancer cells." (PMID 32844745, 2020). "By selectively targeting certain types of cancers, PARP1 inhibitors provide a successful step towards precision medicine in oncology." (PMID 32640701, 2020). "Several PARP-1 inhibitors have been developed for cancer therapy and are currently available, including olaparib, niraparib, rucaparib, veliparib, and talazoparib." (PMID 32903806, 2020). "Recently, drug synergy between BET inhibitors and PARP-1 inhibitors in breast, ovarian, prostate, and pancreatic HR-proficient cancer cells was reported." (PMID 33339368, 2020). "Our work points to the synergism between KLF4 and PARP1 in tumorigenesis and cancer therapy, which provides a potential new therapeutic strategy for killing BRCA1‐proficient triple‐negative breast cancer cells." (PMID 33231937, 2020).
cancer (continued). "PolyADP ribosylation by PARP1 is a prominent mechanism of protein activity modulation in cancer cells." (PMID 32455851, 2020). "In cells that have a deficiency in homologous recombination repair, PARP1 trapping results in double-stranded lesions and eventually leads to cell death, providing an opportunity for targeted therapy in BRCA-mutant cancer cells." (PMID 31640753, 2019). "Modulating the PARylation pathway as an approach to anti-cancer therapy has been an area of intensive investigation in recent years, especially inhibition of PARylation synthesis through the use of PARP1/2 inhibitors." (PMID 30459355, 2019). "Of interest, PARP1 proficiency in cancer cells is required for APO866 to be cytotoxic in these cells." (PMID 31803365, 2019). "In this trial cancer patients will be evaluated for the response to AZD-1775 in combination with the PARP-1 inhibitor, olaparib." (PMID 31717700, 2019). "PARylation plays an important role in the remodelling and repair of impaired replication forks, providing a rationale for targeting highly replicative cancer cells with PARP1/2 inhibitors." (PMID 31408463, 2019). "In this study, we have identified a novel role of HMGA2 in enhancing DNA damage‐induced PARP1 activity and diminishing the sensitivity of cancer cells to the PARP inhibitor olaparib." (PMID 30289618, 2019). "PARP-1, a protein involved in the response to single and double strand DNA breaks and important to many cancers, was confirmed for interaction after pulldown of the endogenous HNF4α from both HT-29 and LoVo cells." (PMID 31060309, 2019). "Poly (ADP-ribose) polymerase 1 (PARP1) has emerged as an attractive target for cancer therapy due to its key role in DNA repair processes." (PMID 30551210, 2019). "Due to its role in oxidative stress and inflammatory responses, PARP-1 is also involved in several diseases other than cancer." (PMID 31877876, 2019). "This combinational approach with PARP1 inhibitors has been already used with success in specific cancers and several clinical trials are ongoing." (PMID 31105872, 2019). "The PARP-1/2 inhibitor Olaparib (OLA, Lynparza, AZD-2281) has been approved by U.S. Food and Drug Administration (FDA) to treat certain cancers, especially in BRCA-mutated patients (ucm572143, ucm592357, and NCT02987543)." (PMID 30691122, 2019). "PARP1 participates in several types of DNA repair and is an important drug target for cancer therapy." (PMID 31291457, 2019). "Recently, the therapeutic application of PARP-1 inhibitors has received considerable attention because of its potential in treating cancer, inflammatory diseases, neurodegenerative diseases and several other diseases." (PMID 31766720, 2019). "This work demonstrates the function of PARP1 in DNA DSB repair, laying the foundation for applying PARP1 inhibitors to cancer treatment by inhibiting the hyper-activated HR repair machinery in tumors." (PMID 31291457, 2019). "While PARP‐1 inhibition is an attractive therapeutic target in cancer owing to its role in regulating DNA damage, it also prevents cell death in certain conditions." (PMID 30804002, 2019). "The PARP1 inhibitor olaparib has been approved and has achieved success in the treatment of BRCA-mutated cancers in the basis of this synthetic lethality approach." (PMID 30813388, 2019). "Taken together, these results indicate that combining PARP1 inhibitors and chemicals inducing DNA DSBs holds the potential to treat HR proficient cancers." (PMID 31291457, 2019). "Owing to its decisive role in DNA repair, the inhibition of PARP1 has emerged as a prominent therapeutic option in cancer treatment, either to potentialize the cytotoxic action of chemotherapy or radiation therapy or to target repair-deficient tumors." (PMID 31281570, 2019). "PARP-1 gene plays an essential part in base excision repair pathway and its functional variations result in several types of cancer." (PMID 31609976, 2019).